C1orf54 (chromosome 1 open reading frame 54)
Synonyms: FLJ23221
Tractability: Antibody: UniProt places it where antibodies can reach, with high confidence; UniProt predicts a signal peptide or a membrane-spanning region; its Gene Ontology location is reachable by antibodies, with medium confidence; the Human Protein Atlas places it where antibodies can reach.
Gene: Protein-coding gene on chromosome 1 (150,268,034 to 150,281,735, forward strand). Ensembl gene ENSG00000118292.
Subcellular location: Secreted
Subcellular location (Human Protein Atlas): Plasma membrane; Predicted to be secreted
Gene Ontology:
Cellular component: extracellular region
Genetic constraint (gnomAD): Loss-of-function variants: 5 observed, 7.95 expected, observed/expected ratio (o/e) 0.63, 90% interval 0.33 to 1.32. That is too few expected variants to judge how well the gene tolerates losing a copy. Missense variants: 108 observed, 113.17 expected, observed/expected ratio (o/e) 0.95, 90% interval 0.82 to 1.12. Synonymous variants: 43 observed, 40.51 expected, observed/expected ratio (o/e) 1.06, 90% interval 0.83 to 1.37.
Homologues: Orthologues: chimpanzee C1H1orf54 (98% identical), macaque C1H1orf54 (93% identical), pig C1orf54 (79% identical), rabbit C1orf54 (72% identical), guinea pig C1orf54 (66% identical), mouse BC028528 (64% identical), rat C2h1orf54 (63% identical), dog C1orf54 (60% identical).
Diseases named in the same sentence as C1orf54 in open-access papers:
C1orf54 is named in the same sentence as 8 diseases in open-access papers, as found by Europe PMC text mining. Sharing a sentence is not in itself a finding about the gene and the disease. The quoted sentences say what the papers report.
bipolar disorder (1 paper, 2023). A disorder of the brain that causes unusual shifts in mood, energy, activity levels and the ability to carry out day-to-day tasks. "Potential candidate genes for bipolar disorder with metabolic syndrome were found in 5 candidate genes (AP1G2, C1orf54, DMAC2L, RABEPK and ZFAND5), all of which have diagnostic significance." (PMID 37860165, 2023).
carotid artery aneurysm (1 paper, 2022). "Turley and coworkers also suggested that a secreted protein, encoded by C1orf54, is associated with SCAD; C1orf54 has previously been linked to carotid artery aneurysm, although the function of this protein is still unknown." (PMID 36561772, 2022).
renal fibrosis (1 paper, 2018). A final common manifestation of a wide variety of chronic kidney diseases characterized by glomerulosclerosis and tubulointerstitial fibrosis. "C1orf54 overexpression significantly decreased serum BUN and creatinine starting from Day 3 post‐IRI and increased Ki‐67+ cell numbers and alleviated renal fibrosis post‐IRI." (PMID 29999589, 2018).
C1orf54 also shares sentences with these, for which no sentence is quoted: kidney (1 paper); kidney injury (1); metabolic syndrome (1); myocardial infarction (1); systemic lupus erythematosus (1).